N4BP2L1 (NEDD4 binding protein 2 like 1)
Description:
Might play a role in adipocyte differentiation and triglyceride accumulation.
Synonyms: CG018
Tractability: No criterion of Open Targets' tractability assessment is met for any kind of drug.
Gene: Protein-coding gene on chromosome 13 (32,400,723 to 32,428,311, reverse strand). Ensembl gene ENSG00000139597.
Subcellular location (Human Protein Atlas): Cytosol
Genetic constraint (gnomAD): Loss-of-function variants: 12 observed, 21.18 expected, observed/expected ratio (o/e) 0.57, 90% interval 0.36 to 0.92. The upper end of that interval is the gene's LOEUF score, 0.92, which puts it in group 3 of 6, group 1 being the genes least tolerant of losing a copy. Missense variants: 258 observed, 306.54 expected, observed/expected ratio (o/e) 0.84, 90% interval 0.76 to 0.93. Synonymous variants: 104 observed, 109.87 expected, observed/expected ratio (o/e) 0.95, 90% interval 0.81 to 1.11.
Homologues: Orthologues: chimpanzee N4BP2L1 (99% identical), macaque N4BP2L1 (99% identical), dog N4BP2L1 (93% identical), pig N4BP2L1 (88% identical), guinea pig N4BP2L1 (83% identical), mouse N4bp2l1 (83% identical), rat N4bp2l1 (82% identical), tropical clawed frog N4BP2L1 (44% identical). Paralogues in human: N4BP2 (40% identical), N4BP2L2 (37% identical).
Diseases named in the same sentence as N4BP2L1 in open-access papers:
N4BP2L1 is named in the same sentence as 7 diseases in open-access papers, as found by Europe PMC text mining. Sharing a sentence is not in itself a finding about the gene and the disease. The quoted sentences say what the papers report.
breast carcinoma (1 paper, 2024). "In addition, protein and RNA expression analysis of TCGA-BRCA revealed N4BP2L1 as a promising diagnostic protein biomarker in breast cancer." (PMID 38859961, 2024).
nasopharyngeal carcinoma (1 paper, 2018). A carcinoma arising from the nasopharyngeal epithelium. "Although N4BP2L1 is a critical paralog of N4BP2, highly expressed in nasopharyngeal carcinoma, little information was available about the functional role of N4BP2L1 in tumor cells." (PMID 30115834, 2018).
ovarian carcinoma (1 paper, 2020). A malignant neoplasm originating from the surface ovarian epithelium. "Both BRCA2 and STARD13 are well known tumor-suppressors, and upregulation of N4BP2L1 and N4BP2L2 has been associated with positive prognosis in ovarian cancer cases." (PMID 32404140, 2020).
tumor (3 papers, 2018 to 2022). "Second, the survival analysis showed that 7 genes had significant (p < 0.05) Kaplan–Meier curves, including 5 genes (MS4A1, N4BP2L1, IGF1R, TCF7L2 and COL11A1) based on the normal expression, and 2 genes (TCF7L1 and PTPRM) based on the tumor expression." (PMID 35406404, 2022).
N4BP2L1 also shares sentences with these, for which no sentence is quoted: cancer (2 papers); breast tumor (1); Cachexia (1).